SND1 (staphylococcal nuclease and tudor domain containing 1)
Description:
Endonuclease that mediates miRNA decay of both protein-free and AGO2-loaded miRNAs. As part of its function in miRNA decay, regulates mRNAs involved in G1-to-S phase transition. Functions as a bridging factor between STAT6 and the basal transcription factor. Plays a role in PIM1 regulation of MYB activity. Functions as a transcriptional coactivator for STAT5 (By similarity). (Microbial infection) Functions as a transcriptional coactivator for the Epstein-Barr virus nuclear antigen 2 (EBNA2). (Microbial infection) Promotes SARS-CoV-2 RNA synthesis by binding to negative-sense RNA and the viral protein nsp9.
Synonyms: TDRD11; p100; TSN; Tudor-SN
Tractability: Small molecule: a structure with a bound ligand is known. PROTAC: UniProt records ubiquitination sites on it; ubiquitination databases record sites on it; its protein half-life has been measured.
Target class: Enzyme; Hydrolase
Gene: Protein-coding gene on chromosome 7 (127,652,145 to 128,092,609, forward strand). Ensembl gene ENSG00000197157.
Subcellular location: Cytoplasm; Nucleus; Melanosome
Subcellular location (Human Protein Atlas): Cytosol
Pathways (Reactome):
Disease: Signaling by BRAF and RAF1 fusions
Gene Ontology:
Molecular function: 3' overhang single-stranded DNA endodeoxyribonuclease activity; cadherin binding; endonuclease activity; protein binding; RISC complex binding; RNA binding; RNA endonuclease activity; transcription coregulator activity; nuclease activity; nucleic acid binding
Biological process: miRNA catabolic process; mRNA catabolic process; negative regulation of apoptotic process; osteoblast differentiation; regulation of cell cycle process; regulatory ncRNA-mediated gene silencing
Cellular component: cytoplasm; cytosol; extracellular exosome; melanosome; membrane; nucleus; dense body; RNAi effector complex
Genetic constraint (gnomAD): Loss-of-function variants: 30 observed, 105.48 expected, observed/expected ratio (o/e) 0.28, 90% interval 0.21 to 0.39. The upper end of that interval is the gene's LOEUF score, 0.39, which puts it in group 1 of 6, group 1 being the genes least tolerant of losing a copy. Missense variants: 823 observed, 1,162.7 expected, observed/expected ratio (o/e) 0.71, 90% interval 0.67 to 0.75. Synonymous variants: 385 observed, 440.83 expected, observed/expected ratio (o/e) 0.87, 90% interval 0.8 to 0.95.
Homologues: Orthologues: chimpanzee SND1 (99% identical), macaque SND1 (99% identical), dog SND1 (99% identical), pig SND1 (99% identical), guinea pig SND1 (98% identical), mouse Snd1 (97% identical), rat Snd1 (97% identical), rabbit SND1 (95% identical), tropical clawed frog snd1 (87% identical), zebrafish snd1 (85% identical), Drosophila melanogaster Tudor-SN (51% identical), Caenorhabditis elegans tsn-1 (47% identical). Paralogues in human: STK31 (16% identical).
Diseases named in the same sentence as SND1 in open-access papers:
SND1 is named in the same sentence as 70 diseases in open-access papers, as found by Europe PMC text mining. Sharing a sentence is not in itself a finding about the gene and the disease. The quoted sentences say what the papers report.
hepatocellular carcinoma (27 papers, 2012 to 2025). A malignant tumor that arises from hepatocytes. "It was reported that the highly expressed SND1 was associated with a chronic inflammatory state of hepatocellular carcinoma cells." (PMID 34608846, 2021). "For instance, MGLL was reported as a potential tumor suppressor in hepatocellular carcinomas, associated with its loss of protein expression, which was posttranslationally dictated by SND1-promoted ubiquitination for proteasome-mediated proteolysis." (PMID 27366945, 2016). "Promoter activity of the cell growth- and RNA-protection associated SND1 gene is up-regulated by ER stress in human hepatoma cells." (PMID 25494629, 2014). "Specifically, SRSF9 and SND1 have been found overexpressed in several tumor pathologies, such as breast cancer, bladder cancer, glioblastoma, melanoma, or hepatocellular carcinoma, where they have been associated with an increase in cell proliferation, invasion and poor prognosis." (PMID 31561558, 2019). "In this study, SND1, one of the highly upregulated proteins affecting the patient’s survival during liver carcinoma, has been taken as our inhibitor target." (PMID 40841409, 2025). "A previous study revealed that SND1 promotes tumor angiogenesis in human hepatocellular carcinoma, suggesting its involvement in modulating tumor vasculature and cancer progression." (PMID 39895626, 2025). "Recently, Snd1 was suggested to promote hepatocellular carcinoma by binding and degrading the Protein Tyrosine Phosphatase Nonreceptor Type 23 (PTPN23) mRNA." (PMID 37151849, 2023). "In hepatocellular carcinoma, SND1 has been shown to be involved in controlling cell growth and proliferation." (PMID 34378960, 2021). "For example, human SND1 can promote the proliferation of hepatocellular carcinoma cell lines and takes part in the occurrence of hepatocellular carcinoma." (PMID 34608846, 2021). "More recently, it was found that hepatoma cells overexpressing SND1 display low triglyceride synthesis and accelerated cholesterol ester synthesis, likely because fatty acids are preferentially used for cholesterol esterification." (PMID 33768972, 2021). "The overexpression of SND1 protein in hepatoma cells contributes to the accumulation of cholesteryl esters, leading to more cholesterol esterification via fatty acid and the limitation of triglyceride synthesis." (PMID 34608846, 2021). "In hepatocellular carcinoma, the up-regulation of SND1 expression can influence the cellular cholesterol distribution and homeostasis." (PMID 34608846, 2021). "SND1 has been reported to contribute to tumor progression and metastasis in various types of tumors, including glioma, breast cancer and hepatocellular carcinoma." (PMID 31978894, 2020). "We reported the activation of SND1 transcription and the nucleocytoplasmic redistribution of SND1 protein during the inflammatory response prompted by TNFα in human hepatoma cells." (PMID 30619748, 2018). "We anticipate the contribution of a SREBPs/SND1 pathway to lipid metabolism reprogramming of human hepatoma cells." (PMID 29296233, 2017). "Our findings uncover SND1 as a novel target gene for SREBPs that is induced by SREBP-2 activation upon conditions of sterol depletion in the hepatoma cell and repressed by SREBP-1." (PMID 29296233, 2017). "Such contrasting effects of SREBP-2 and SREBP-1a and -1c on SND1 gene promoter transcriptional rate point to a dual regulatory mechanism for SND1 expression in hepatoma cells." (PMID 29296233, 2017). "Recently, it has been shown that SND1-overexpressing hepatocellular carcinoma cells present an increased de novo cholesterol synthesis and cholesteryl ester accumulation." (PMID 29296233, 2017). "Altogether these results are consistent with the concept that there is a sterol-sensitive mechanism of transcriptional regulation operating for the SND1 gene in human hepatoma cells which seems to be somewhat less operative in HEK293 cells." (PMID 29296233, 2017).
hepatocellular carcinoma (continued). "It has been shown that the expression of human TSN (a.k.a., SND1) is upregulated in various human cancers such as colon, prostate, breast, and hepatocellular cancers." (PMID 26808625, 2016). "It has been detected that SND1 expression increases in human tumors such as prostate, breast, colon, and hepatocellular carcinomas, and is positively related to the stages and grades of cancer." (PMID 25965817, 2015). "The staphylococcal nuclease and tudor domain containing 1 (SND1) is a multifunctional protein overexpressed in breast, prostate, colorectal and hepatocellular carcinomas and malignant glioma." (PMID 25405367, 2015). "Collectively, these results support the concept that, in liver carcinoma, there is an intertwined relationship between SND1 gene expression and tumour environment inflammation, conditions that are closely linked to ER stress." (PMID 25494629, 2014). "Here, we seek to extend the previous knowledge of gene transcriptional regulation and have analyzed the transcriptional response of human SND1 gene to pharmacological activation of the UPR in human hepatoma cells." (PMID 25494629, 2014). "SND1 has been shown to trigger a novel molecular cascade that, mediated by miR-221 and NF-κB activation, leads to induction of angiogenic factors for hepatocellular carcinoma progression." (PMID 25494629, 2014). "Interestingly and in accordance with our KO model, transgenic overexpression of Snd1 in mouse liver has been shown to result in chronic inflammatory state with partial penetrance to hepatocellular carcinoma." (PMID 37151849, 2023). "Scholarship generally concludes that the inhibition of SND1 nuclease activity by pdTp could be an effective intervention or therapeutic strategy for hepatocellular carcinoma." (PMID 36557606, 2022). "As an oncogene in hepatic carcinoma, SND1 enhances inflammation and fibrosis, suggesting that SND1 could be an important link between SREBP2 and cellular stress responses including inflammation." (PMID 36566329, 2022). "Also, the highly expressed SND1 expression affects the cholesterol distribution and homeostasis of hepatocellular carcinoma cells." (PMID 34608846, 2021). "The data contain information related to the research article entitled “Profiling of promoter occupancy by the SND1 transcriptional coactivator identifies downstream glycerolipid metabolic genes involved in TNFα response in human hepatoma cells” (DOI: 10.1093/nar/gkv858)." (PMID 31667320, 2019). "Consistent with this, we recently documented that, in human hepatoma HepG2 cells, nuclear SND1 interacted with the genomic DNA to hook SND1 on the promoter of a broad number of target genes modulating cell growth, oncogenic transformation, viral infection and metabolic regulation." (PMID 30619748, 2018). "Our findings here reported about the SREBP-2-mediated activation of SND1 transcription in response to sterol-lowering treatments are consistent with a recent study in rat hepatoma cells overexpressing SND1 that evidence a constitutive overactivation of the SREBP-2 regulatory system." (PMID 29296233, 2017). "In parallel, we found that simvastatin or LPDS significantly up-regulated (3-fold or 1.6-fold) the expression of SND1 mRNA in human hepatoma cells and that SND1 protein accumulated in both the nucleus and the cytoplasm of simvastatin-treated cells, though it was not significantly altered by LPDS." (PMID 29296233, 2017). "Overall, our findings uncover an unexpected large set of potential SND1 target genes and partners and reveal SND1 to be a determinant downstream effector of TNFα that contributes to support glycerophospholipid homeostasis in human hepatocellular carcinoma during inflammation." (PMID 26323317, 2015). "SND1 involvement in the degradation of tumor suppressor mRNA as a part of RISC machinery that shows elevated activity in human hepatocellular carcinoma (HCC) cells." (PMID 34809722, 2021).
hepatocellular carcinoma (continued). "Staphylococcal nuclease domain-containing 1 (SND1) is a multifunctional protein that is overexpressed in multiple cancers, including hepatocellular carcinoma (HCC)." (PMID 26258795, 2015). "A recent article showed that staphylococcal nuclease and Tudor domain-containing 1 (SND1) was bound to the 3′ untranslated region of OAT2 mRNA and inhibited OAT2 translation, resulting in reduced OAT2 protein expression in hepatocellular carcinoma cells." (PMID 39598479, 2024). "Aberrant expression of SND1 and PGAM5 predicts poor outcomes in hepatocellular carcinoma (HCC) patients." (PMID 35433434, 2022). "Hepatocellular carcinoma (HCC) is an example of a cancer type that often displays elevated PRMT5 and SND1 levels, and there is evidence that hyperactivation of this axis is oncogenic." (PMID 33768972, 2021). "Here we attempt to decipher the transcriptional control of SND1 gene by SREBP-2 and SREBP-1 transcription factors in human hepatoma cells." (PMID 29296233, 2017). "For instance, the binding of SND1 to the 3′UTR of PTPN23 (protein tyrosine phosphatase nonreceptor type 23) mRNA in human hepatocellular carcinoma (HCC) promotes its RNA degradation." (PMID 36557606, 2022).
breast carcinoma (23 papers, 2015 to 2025). "Overexpression of MTDH and SND1 in primary tumors is strongly associated with reduced metastasis-free survival in multiple large-scale datasets of breast cancer patients." (PMID 31737791, 2019). "A recent study reported a close association between SND1 upregulation and TGFβ1/Smad signaling pathway activation in order to promote epithelial-to-mesenchymal transition in breast cancer." (PMID 30619748, 2018). "We further observed that Linc00668 associated with SND1 in breast cancer cells." (PMID 32117742, 2020). "While the disruption of the SND1–MTDH interaction has been previously characterized in breast cancer, its downstream effects in ovarian cancer remain largely unexplored." (PMID 41286067, 2025). "For example, in breast cancer, linc00668 recruits SND1 to the promoters of stemness factors, while during limb development, lncRNA-HIT recruits SND1 in complex with CREB-binding protein (CBP) to regulate the transcription of pro-chondrogenic genes." (PMID 39169000, 2024). "MTDH depletion or pharmacological inhibition disrupts the interaction with staphylococcal nuclease domain-containing 1 (SND1), which is required to sustain breast cancer progression in established tumors." (PMID 38727283, 2024). "For example, in breast cancer, SND1 activates the expression of stemness factors by localizing to their promoters through the recruitment of linc0066842." (PMID 39169000, 2024). "The interaction between MTDH and SND1 is critical for its oncogenic function in breast cancer and disruption of this interaction results in suppression of cancer progression and metastasis." (PMID 37973913, 2023). "In this study, we discovered that SND1 induces the transcription of DNA methyltransferase 3A (DNMT3A) in breast cancer cells." (PMID 37885030, 2023). "Studies in breast cancer models revealed that the primary function of MTDH in cancer involves interaction with SND1 and protection from degradation." (PMID 37973913, 2023). "Previous studies have shown that SND1 can promote the invasion and migration of breast cancer cells." (PMID 37885030, 2023). "In this study we observed that Linc00668 promoted breast cancer cell invasion, stem-cell like capacity, and Dox resistance via its binding to SND1." (PMID 32117742, 2020). "SND1 has been reported to play an important role in epithelial-mesenchymal transition, tumor initiation, and tumor progression of breast cancer, as well as in other types of cancer." (PMID 32117742, 2020). "Linc00668 depletion led to reduced expression of the downstream target of SND1 and further attenuated the self-renewal capacity of breast cancer cells." (PMID 32117742, 2020). "Our observations suggest that Linc00668 promotes metastasis, and chemotherapeutic resistance in breast cancer by interacting with SND1." (PMID 32117742, 2020). "We then focused on the transcriptional activator, SND1, which was reported to promote breast cancer metastasis, and tumor initiation." (PMID 32117742, 2020). "As it was suggested above that SND1 mediated Linc00668 function in breast cancer cells, we also examined the function of SND1 in breast cancer cells." (PMID 32117742, 2020). "SND1 was one of these proteins, deregulated in breast cancer metastasis and showed significant differential expression in normal versus breast cancer tissue." (PMID 25405367, 2015). "iTRAQ based proteomic analysis of a breast cancer metastasis model revealed that SND1 levels are upregulated with carcinoma progression." (PMID 25405367, 2015). "A study aimed at exploring role of AEG1 in breast cancer metastasis, identified SND1 as an AEG-1 interacting protein." (PMID 25405367, 2015). "Analysis of clinical data set of breast cancer patients with metastasis revealed that SND1 levels strongly correlate with lung metastasis incidence and metastasis-free survival." (PMID 25405367, 2015).